CEBPD (CCAAT enhancer binding protein delta)
Diseases named in the same sentence as CEBPD in open-access papers (continued):
Sharing a sentence is not in itself a finding about the gene and the disease.
psychiatric disease (2 papers, 2017 to 2024). "However, it remains unclear whether the underlying molecular mechanism that accelerates neuroinflammation through CEBPD activation contributes to the development of psychiatric disorders, particularly bipolar mania." (PMID 38419037, 2024).
cardiovascular diseases (1 paper, 2025). "Aberrant CEBPD expression and activity are associated with multiple organ diseases, including cardiovascular diseases." (PMID 40087290, 2025). "This review discusses the basic molecular and biological properties of CEBPD, and its crucial roles in cardiovascular diseases." (PMID 40087290, 2025). "Various studies have shown that CEBPD expression in cardiomyocytes, epicardial cells, macrophages, VSMCs, and endothelial cells plays vital roles in cardiovascular diseases." (PMID 40087290, 2025). "Given that elevated CEBPD levels play an important role in the pathogenesis of cardiovascular diseases, suppressing CEBPD expression or activity is a promising strategy for treating these diseases." (PMID 40087290, 2025). "In addition, accumulating evidence has shown that CEBPD plays a vital role in cardiovascular diseases." (PMID 40087290, 2025). "Finally, we discuss the contribution of CEBPD to cardiovascular diseases and highlight the strategies for developing novel therapies targeting CEBPD." (PMID 40087290, 2025).
immune dysfunction (1 paper, 2024). "Our study suggested that CEBPD expression in AMI patients was upregulated compared to stable CAD, implying excessive inflammation and immune dysfunction might exert pivotal function during CAD progression." (PMID 38451044, 2024).
CEBPD also shares sentences with these, for which no sentence is quoted: prostate carcinoma (8 papers); melanoma (6); myotonic dystrophy (5); bacterial infections (4); lung adenocarcinoma (4); astrocytoma (3); cardiac hypertrophy (3); cardiomyopathy (3); chronic myelogenous leukemia (3); dilated cardiomyopathy (3); infectious disease (3); lung fibrosis (3); pneumococcal meningitis (3); squamous cell carcinoma (3); breast invasive carcinoma (2); ductal adenocarcinoma (2); fibrosis (2); heart failure (2); low grade glioma (2); meningitis (2); myotonic dystrophy type 1 (2); peritonitis (2); pneumonia (2); renal fibrosis (2); skin cancer (2); adenoma (1); ampullary carcinoma (1); amyloid (1); anaplastic astrocytoma (1); autoimmune encephalitis (1).
A further 55 diseases each share a sentence with CEBPD in 1 paper.